TNC (tenascin C)
Diseases named in the same sentence as TNC in open-access papers (continued):
Sharing a sentence is not in itself a finding about the gene and the disease.
tumor (continued). "To further validate our findings in TNBC patient samples, we analyzed the correlations among TNC, LC3B and CD8+ T cells in these tumours." (PMID 32732922, 2020). "To elucidate the origin of TGFBI, TNC, and FN1 in HGSC ascites, we made use of our transcriptome, proteome, and secretome datasets for tumor cells, TAMs, and TATs7,33." (PMID 32312959, 2020). "CagA+Vac+ H. pylori infection results in the upregulation of HIF-1α and tenascin-C (TNC), enhancing EMT and tumor progression, the release of proangiogenic factors, and further CAFs activation." (PMID 32340207, 2020). "As well as increasing tumor vasculature, VEGF also upregulates expression of the macromolecules tenascin C (TNC) and periostin." (PMID 33178210, 2020). "Tenascin C (TNC) is an important integrin partner in stromal cells, which participates in many aspects of tumor progression." (PMID 32019108, 2020). "Interaction between annexin II (ANX2), a calcium-dependent phospholipid-binding protein expressed on tumor cells, and the ECM protein tenascin C (TNC) contribute to EMT and anoikis resistance and stemness in PDA." (PMID 32780245, 2020). "TGFBI and TNC both bind to integrins and, in case of TNC, additionally to EGF receptors present on the surface of tumor cells, thereby activating migration-inducing pathways." (PMID 32312959, 2020). "Tenascin-C (TNC) is an extracellular matrix (ECM) glycoprotein that plays an important role in cell proliferation, migration, and tumour invasion in various cancers." (PMID 32817625, 2020). "We previously detected increased expression of Tenascin-C (TNC) protein in DIPG cerebrospinal fluid and tumor tissue relative to normal specimens." (PMID 31092287, 2019). "A large scale retrospective study, analyzing data of these 502 glioblastoma patients treated with tenascin-C-directed PRIT, reported a median survival of 19 months with 8% of patients showing tumor mass reduction and 28% presenting stable disease." (PMID 31480515, 2019). "Tenascin-C (TNC), one of the typical matricellular proteins, is highly expressed in inflammatory lesions and tumor tissues." (PMID 31195598, 2019). "Tenascin-C (TNC) expression is involved in fetal tissue development and neoplasia in different organs, and it also facilitates the formation of cancer stroma, including desmoplasia and angiogenesis." (PMID 31632476, 2019). "In these studies, we detected increased expression of Tenascin-C (TNC) protein in DIPG CSF and tumor tissue relative to normal specimens." (PMID 31092287, 2019). "RNA sequencing identified upregulation of an oncogene, Tenascin-C (TNC) and downregulation of several tumor suppressors in BT-474 NRP-1 cells." (PMID 29728077, 2018). "Fibroblasts expressing TGM2 were observed throughout the tumour stroma, while the expression of PDPN and TNC is lower and more restricted." (PMID 29551776, 2018). "Overlap with tenascin-C and α-SMA was observed in tumor bulk (26% (SD 32)), and tumor invasive front (13% (SD 15))." (PMID 28978001, 2017). "It is known that both TNC and MMP are strongly expressed in tumor tissue; in addition, there are reports that TNC aggravates the MMP production of cancer cells." (PMID 28106752, 2017). "In this study, we present evidence that TNC activates JNK/c-Jun signalling, resulting in induction of EMT and transcriptional activation of MMP9 to enhance the metastatic properties of tumour cells." (PMID 29088796, 2017). "With a pilot series of 12 patients we observed overlap of tenascin-C, fibronectin and α-SMA expressions in tumor stroma and in cytoplasm of stromal cells suggesting that myofibroblasts contribute to stromal tenascin-C and fibronectin synthesis." (PMID 28978001, 2017). "Tenascin-C (TNC) and alternatively spliced forms of fibronectin (FN) are principle ECM components of the angiogenic vasculature of tumours, yet barely detected in quiescent adult vessels (reviewed in2)." (PMID 28986537, 2017).
tumor (continued). "TNC is a large ECM glycoprotein that belongs to this family of DAMPs and is highly expressed in tumor tissue in the majority of malignant solid tumors." (PMID 27612200, 2016). "Stable cell lines engineered to secrete minimal levels of FN showed a concomitant increase in secretion of Tenascin-C and became sensitive to BRAFV600E and ERK inhibition as clonally- derived 3D tumor aggregates." (PMID 26944546, 2016). "Tenascin C showed a very weak correlation, E-cadherin a weak to moderate correlation, and TTF-1 a strong correlation with tumor proliferation." (PMID 27409604, 2016). "In this study, expressions of Tenascin-C and CAF markers in 136 human ESCC samples and 20 adjacent non-tumor esophageal mucosa samples were examined using immunohistochemical examinations on tissue microarray slides." (PMID 26731558, 2016). "Both TNC and GDF15 were found in the cytoplasm of the nevoid cells, with significantly higher expression levels in the tumor cells compared with normal cells." (PMID 26540631, 2015). "Through the basis of annotation suggesting that PTK2, CTTSL1, TNC, ETS1 and HSP90AA1 were involved in tumor cell proliferation, prevent tumor cell from apoptosis and promote tumor cell invasion in oral carcinogenesis." (PMID 23405089, 2013). "Noticeably, the expression of all mesenchymal markers analyzed (N-CAD, TNC, VIM and FN 1) was significantly higher in the tumor cells than in the Nthy.ori 3.1 thyrocytes." (PMID 24069422, 2013). "Such genes as Tenascin-C, Osteopontin and MMP, which were reported to contribute to tumor metastasis, were inhibited by Sal B in this study." (PMID 21726465, 2011). "TNC may therefore act as a modulator of early migratory events, which include substrate sensing and adhesion, and may promote cell migration by reducing cell adhesiveness to FN, thus inducing a more dynamic interaction between the tumor cell and the ECM components." (PMID 21747918, 2011). "A prominent topic of current research is TNC, an ECM protein that plays a key role in the development of multicellular organisms, as well as in pathological processes such as inflammation, tissue injury, tumor angiogenesis, and metastasis." (PMID 40981103, 2025). "Altered molecular targets, such as E-cadherin (CDH1), MMP9, Survivin (BIRC5), Cytokeratin 5 (KRT5), VEGFA, IL15, TNF-α (TNF), TRAIL (TNFSF10), and Tenascin-C (TNC), exhibited increased expression in our study, which correlates with their upregulation in tumor samples from individuals with OC." (PMID 40072102, 2025). "The extradomain A1 of tenascin-C is a non-internalizing extracellular matrix protein highly expressed in multiple tumor types, including HNSCC, and represents an appealing imaging target." (PMID 41211421, 2025). "TNC, a hexameric glycoprotein, has been known to increase tumor invasion and metastasis in nonthyroid cancers." (PMID 39951495, 2025). "TNC, for instance, has been shown to enhance the activation of growth factor signaling pathways such as EGFR and Wnt/β-catenin, thereby promoting increased tumor cell survival and division." (PMID 40699660, 2025). "TENASCIN signaling (primarily Tenascin‐C, TNC) remodels the ECM and increases matrix stiffness via integrin–FAK/SRC and mechanotransduction pathways, activates YAP/TAZ, and consequently enhances tumor cell adhesion, migration, and immune exclusion." (PMID 41498033, 2025). "Additionally, TENASCIN was frequently observed in the HAS group, with tumor cells in this group interacting with other cells, including tumor cells themselves, via TNC - SDC1/SDC4 or TNC - ITGA8_ITGB1/ITGAV_ITGB6." (PMID 39267750, 2024). "In addition, the on-chip expression profiling showed that the expression of the hepatic stellate cell-related genes FAP, SPARC, and TNC, especially FAP, was upregulated in tumor tissues compared to normal tissues." (PMID 38740736, 2024). "In addition, we also identified several key genes involved in tumor aggressiveness, including COL5A1, VEGFA, TNC, and FN1." (PMID 38390494, 2024).
tumor (continued). "The GBM core is stiffer, denser, and is rich in ECM proteins hyaluronic acid and tenascin-C when compared to tumor rim and non-neoplastic tissues." (PMID 38946776, 2024). "However, they significantly differed in terms of marker genes (AKR1C1, FOSL1, LIF, and THAP2 vs. WNT5A, GREM1, TNC, and MMP1), tissue origins (normal vs. tumor), and organ preferences." (PMID 38744958, 2024). "The most enriched glycoproteins in tumour ECM compared to non-tumour ECM included thrombospondin-2 (16.9-fold), MXRA5 (14.4-fold), peroxidasin (2.5-fold), thrombospondin-1 (2.5-fold), SPARC (2.3-fold), FRAS1 (2.3-fold) and tenascin-C (2.1-fold)." (PMID 37397358, 2023). "Previous literature dealing with other tumor contexts highlighted the ability of TnC, POSTN, and OPN to regulate several core roles, which orchestrate tumorigenesis and tumor progression, such as proliferation, cell viability, migration, angiogenesis, pro-invasive pathways, and stemness induction." (PMID 36902188, 2023). "TNC was mainly expressed in CAFs, while MMP1 was mostly expressed in tumor cells." (PMID 37007745, 2023). "IHC staining of both cell lines and the primary tumor tissue confirmed a stable expression of CCA tumor markers CK7, CK19, and e-cadherin, and the positive staining of stromal cells for vimentin and CAF markers α-SMA, TNC, and PDGFRB." (PMID 36980644, 2023). "However, under pathological conditions, e.g., tumor progression and metastasis, the ECM can exhibit a particular topology and be enriched in specific components, such as tenascin C (TnC) or osteopontin." (PMID 36980283, 2023). "S100A4+ CAFs promote tumour metastasis through secretion of VEGF-A and Tenascin-C (TN-C)." (PMID 36555218, 2022). "Overall, immunofluorescence revealed that primary fibroblast densities were significantly greater than metastatic astrocyte densities and that the metastatic tumor microenvironment contains more fibrillar collagen I and tenascin C than non-cancerous controls." (PMID 35200398, 2022). "TNC also appears in the tumor-bearing breast in such isoforms, which are absent in the healthy body." (PMID 35268340, 2022). "Tenascin-C may generate barriers for infiltrating T lymphocytes (TIL), thus contributing to the escape from anti-tumor immunity." (PMID 35008401, 2022). "Tenascin-C (TN-C), a member of ECM glycoproteins, is markedly up-regulated in pathologic tissues that are undergoing remodelling, such as those that are suffering inflammation, wound healing, or tumour progression." (PMID 36555218, 2022). "Collagen and tenascin C (TNC) can promote EMT in tumors 64, 65; therefore, the interaction between TSKs and IL7R+ CAFs may mediate the EMT of tumor cells in recurrent cSCC." (PMID 36438481, 2022). "However, NT5E+ cells, TNC+ cells, and PDGFRβ+ cells shifted from ASPN− to ASPN+ in the cribriform tumor microenvironment." (PMID 33600062, 2021). "TNC, together with other ECM molecules such as laminin-5, takes part in the formation of a meshwork functioning as a route for cancer cell invasion, additionally it also stimulates tumor cell invasion by promoting the EMT switch via the Akt/HIF1α axis." (PMID 34199373, 2021). "The triggering of this pathway generated a deleterious inflammatory contexture that helped the tumor escape from immune surveillance and supported a pro-metastatic environment, demonstrating a role for the TLR4 engagement by tenascin-C for tumor growth and spread." (PMID 33718177, 2021). "Instead, the tumor ECM is composed largely of collagen VI, fibronectin, and tenascin C. Analysis of single cell expression data indicates that CAFs may be a major source of tumor ECM production." (PMID 34884982, 2021). "While the overall expression of NT5E, TNC, and PDGFRβ did not change in the tumor microenvironment, ASPN expression was altered in these cells." (PMID 33600062, 2021).
tumor (continued). "In contrast to FAP+ cells and THY1+ cells, the overall percentages of NT5E+ cells, TNC+ cells, and PDGFRβ+ cells were not altered in the tumor microenvironment compared to benign prostate stroma." (PMID 33600062, 2021). "In a recent study, TNC expression in tumour cells of OSCC of the tongue was not a prognosticator of disease progression." (PMID 34205668, 2021). "We therefore targeted tumor cells, immune cells (macrophages, neutrophils, dendritic cells, NK cells and T and B lymphocytes), CAFs, vascular and lymphatic endothelial cells, ECM proteins (fibronectin, tenascin C), and nerve fibers." (PMID 33936105, 2021). "Remarkably, stroma in oral squamous cell carcinomas has lymphoid properties characterized by abundant FRCs expressing extracellular matrix components of lymph nodes including tenascin-C and utilizing CCR7/CCL21 signaling for retaining CD11c+ immune cells in the tumor matrix tracks." (PMID 33912190, 2021). "In PDAC, TNC protein is restrained to the tumor stroma and is not found in epithelial tumor cells or adjacent normal pancreatic tissue." (PMID 33889150, 2021). "Furthermore, FN1, TNC, and TGFBI have been reported to promote tumor migration, invasion, and adhesion, which are functions facilitating metastatic spread." (PMID 32312959, 2020). "Individual contributions of the two phenotypes in “heterogeneous” tumours resulted in major changes in cell–cell junctions and ECM interactions with increased expression of FN1, TNC and matrix re‐modellers, and alterations in the repertoire of collagens and adhesion receptors." (PMID 32145051, 2020). "These secreted proteins were transforming growth factor beta induced (TGFBI), tenascin C (TNC), and fibronectin (FN1), which have in common that they are ECM proteins and as such may provide support for tumor cell adhesion and migration." (PMID 32312959, 2020). "The tumor ECM is composed of a complex mixture of macromolecules, including fibrous proteins (collagen, ELN), proteoglycans (heparan sulfate, chondroitin sulfate), glycosaminoglycans (hyaluronic acid), and glycoproteins (FN1, laminins, TNC)." (PMID 31106200, 2019). "Strong co-expression of TNC and VEGF is also reported in tumor perivascular zones in adult HGG." (PMID 31092287, 2019). "A tenascin-C aptamer, labeled with 18F or 64Cu, demonstrated reliable tumor uptake, compared to a nonspecific scrambled aptamer." (PMID 30682091, 2019). "Our previous analysis of protein and gene expression patterns in DIPG tumor tissue specimens revealed two molecular subgroups of DIPG with relative activation of either Sonic Hedgehog (SHh) or MYCN signaling, with TNC hypomethylation and increased expression in the SHh group." (PMID 31092287, 2019). "The TNC mRNA and protein levels were found to significantly downregulated in tumors without progression compared to those tumors which occurred tumor progression during the follow-up period (P < .05)." (PMID 30633201, 2019). "We recently reported that peptide FNIII14, which inactivated β1-integrin, can delay GBM tumor growth in a xenograft GBM mouse model, suggesting that the tenascin-C/PDGF positive spiral loop might function in vivo." (PMID 31261783, 2019). "Laminin-5 and tenascin-C expressions were considered positive when more than 25% of the tumor cells or areas showed positive staining regardless of the intensity." (PMID 29584696, 2018). "Because Notch signaling is thought to be related to MMP-9 activation, TNC or TNIIIA2 might activate Notch signals through the production of MMP and participate in tumor invasion." (PMID 28106752, 2017). "For example, tenascin-W is enriched in low-grade cancers, while tenascin-C expression is found irrespective of the tumor grade." (PMID 29112161, 2017). "However, after 1–2 cycles of chemotherapy, patients who had PLN involvement at surgery showed significant up-regulation of tumor THBS1, TNC, FN, SPARC and α-SMA expression." (PMID 27487140, 2016).
tumor (continued). "Tumours derived from R132H IDH1 GBM cells expressing the V737N integrin demonstrated increased mechanosignalling, and expressed elevated levels of both HIF1α and TNC." (PMID 27820599, 2016). "In contrast, all four cases of C-cell hyperplasia stained negative for tenascin C. The tumor-staining pattern was homogeneously located in all areas of the tumor." (PMID 27409604, 2016). "Tenascin-C expression (69.1% in stromal fibroblasts and 55.1% in cancer cells) was significantly higher in ESCC tissue samples than in adjacent non-tumor esophageal epithelium (10.0% in stromal fibroblasts and 10.0% in epithelial cells; p < 0.001 and p < 0.001, respectively)." (PMID 26731558, 2016). "This labeled tenascin-C aptamer clearly distinguishes positive tenascin-C tumor from negative tenascin-C tumor." (PMID 28536411, 2015). "At the same time following treatment there was an increased expression of tenascin-C in the stroma, and the α-SMA+ myoepithelial cell layers were reconstituted around the dormant epithelial tumor cells, which displayed a normal mammary gland basal-luminal structure." (PMID 26581390, 2015). "It should also be noted, that CD73, aside of its enzymatic activity in producing adenosine, has been reported to bind to the extracellular matrix protein tenascin C which promotes tumor cell migration in a non-enzymatic fashion." (PMID 25465225, 2014). "The mRNA expression level of six soluble factors already recognized in cancer biology (POSTN, TNC, CSPG2, LOXL1, ATRN, FBS1) increases in response to IGF-I stimulation, suggesting that these factors play some role in stimulating tumour cell proliferation and metastasis." (PMID 20051100, 2010). "Moreover, TNC+/CD81+ EVscorrelated with FLAIR hyperintensity, which besides tumor cell infiltration,might also be indicative of peritumoral edema." (PMID 40056466, 2025). "As an extracellular matrix glycoprotein, TNC is significantly upregulated in processes such as regulating ECM stiffness and EMT, and promoting the formation and maturation of tumor stromal channels, potentially contributing to tumor migration and immune evasion." (PMID 40046232, 2025). "This upregulation of TNC triggers the release of pro-inflammatory factors, such as TNF-α, through TLR4-and STAT3-dependent mechanisms in human macrophages, enhancing the recruitment of M2-like TAMs and boosting their phagocytic activity, thereby inhibiting tumor growth." (PMID 40046232, 2025). "Indeed, enrichment of TNC+ EVs significantlyimproved the detected frequencies of TERT*C228T,reinforcing that the majority of TNC+ EVs in plasma fromglioblastoma patients are specifically released from tumor cells,unlike TNC– EVs." (PMID 40056466, 2025). "Future studies should also delve deeper into the influence of fibronectin on tumor progression, namely, by identifying the specific fibronectin isoforms produced in the tumor, as well as other relevant proteins that have not been covered in this work, such as tenascin-C and versican." (PMID 37190331, 2023). "Examples of key roles played by ECM proteoforms abound in the context of cancer: proteoforms arising from alternative splicing of fibronectin or tenascin-C are specifically detected in tumors but not healthy tissues and have been shown to promote tumor progression." (PMID 36918099, 2023). "In addition to collagens, the ECM of PDAC is composed of TNC and POSTN, which we have previously identified as downstream targets of Prrx1, which fosters liver metastasis in PDAC; therefore, they can be considered key molecules in tumor progression." (PMID 35000025, 2022). "In particular, in our proteomic data, TNC was confirmed to be the most strongly upregulated matrisome protein in RETM918T-driven tumors, while it also appeared to be positively correlated with the abundance of a classical tumor stemness marker PROM1 (CD133) in Mesenchymal tumors." (PMID 36344509, 2022).